RELN (reelin)
Diseases named in the same sentence as RELN in open-access papers (continued):
Sharing a sentence is not in itself a finding about the gene and the disease.
schizophrenia (continued). "RELN expression has been observed to be reduced between 30–50% in different areas of the brain in individuals with schizophrenia compared to healthy controls, which is highly significant given its important role in brain development and connectivity." (PMID 32764320, 2020). "Previous reports have already demonstrated that mice with truncated inactive Reelin exhibit schizophrenia-like behaviors such as hyperactivity, social withdrawal, and memory deficits." (PMID 32982694, 2020). "Conversely, reelin supplementation in the form of a single ventricular injection has been shown to recover schizophrenia-like deficits in mice." (PMID 32580454, 2020). "A Japanese individual with schizophrenia harboring a novel exonic deletion in RELN was recently identified by genome‐wide copy‐number variation analysis." (PMID 32065683, 2020). "The aim of this study was to investigate the effects of chronic Meth on behaviour of HRM and WT mice, with the ultimate aim to better understand the possible role of reelin in schizophrenia." (PMID 32580454, 2020). "We compared the long-term effect of chronic Meth treatment between heterozygous reelin mice (HRM) and wildtype controls (WT) with the aim of better understanding the role of reelin in schizophrenia." (PMID 32580454, 2020). "One of the most studied candidate genes displaying differential methylation in schizophrenia is reelin (RELN)." (PMID 32764320, 2020). "These genes (including RELN) play a central role in the regulation of GABAergic neurotransmission, which is thought to be a significant component of the neuropathology of schizophrenia." (PMID 32764320, 2020). "The HRM carries one mutated reelin gene (RELN) allele and one normal RELN allele leading to a ≈50% reduction in reelin protein levels in the brain, similar to the deficit observed in schizophrenia." (PMID 32580454, 2020). "For instance, genes casually linked to schizophrenia such as Disrupted in schizophrenia-1 (DISC1), Reelin, neuroregulin (NRG), and its receptor, ERBB4, control neuronal migration during brain development." (PMID 30112632, 2019). "Consistently, studies have showed that schizophrenia risk genes (including DISC1, RELN and GLT8D1) have important role in brain development through regulating proliferation and differentiation of neural stem cells." (PMID 30737407, 2019). "Reelin function has been associated with several neurological disorders, such as autism spectrum disorders, schizophrenia, depression, bipolar disorder and AD, and impaired and reduced reelin expression seems to be a common characteristic among them." (PMID 29867379, 2018). "PRS adult offspring showed alterations in the epigenetic regulation of schizophrenia-related gene as reelin, GAD67, BDNF, and mGlu2/3 receptors." (PMID 30564095, 2018). "The first studies on the role of promoter methylation and schizophrenia onset were focused on the epigenetic regulation of reelin expression from the RELN gene." (PMID 28387726, 2017). "Reelin levels were decreased in the post-mortem hippocampal tissue from patients with schizophrenia, bipolar disorder, and depression, and also in an animal model of depression." (PMID 28861331, 2017). "The reduced expression of reelin can weaken the GABAergic neurotransmission in transgenic mice and also schizophrenia or bipolar patients." (PMID 29211814, 2017). "TBR1 pioneer neurons and reelin, which guides cortico-petal migration, were restricted from the schizophrenia cortex." (PMID 30446636, 2017). "Quantitative analysis of reelin immunofluorescence intensity in organoids from three patients and three controls showed a consistent depletion (−40%, p < 0.001) of reelin in the schizophrenia cortex." (PMID 30446636, 2017). "Below we review the evidence that supports reelin as a molecular candidate for the cellular disruptions produced in schizophrenia." (PMID 26968981, 2016).
schizophrenia (continued). "Being sourced from live patients, this cell model encompasses the polygenic nature of schizophrenia, in contrast to simpler RELN-knockout cell and animal models." (PMID 27602387, 2016). "The results demonstrate the first direct evidence for the effects of extracellular reelin in cell migration in schizophrenia." (PMID 27602387, 2016). "Genes such as COMT and REELIN, as well as a few others in the dopaminergic, serotonergic and GABAergic pathways, have also shown differential methylation profiles in schizophrenia samples." (PMID 28117656, 2016). "The reelin gene is a strong candidate in the etiology of several psychiatric disorders such as schizophrenia, major depression, bipolar disorders, and autism spectrum disorders." (PMID 28127276, 2016). "Our results demonstrate for the first time, reelin-dependent functional deficits in cells derived from patients with schizophrenia." (PMID 27602387, 2016). "In patients with schizophrenia, an aberrant distribution of interstitial cells and reduced reelin mRNA levels have been detected in the prefrontal cortex and in the hippocampal formation." (PMID 27064909, 2016). "Members of the semaphorin family, and semaphorin 3a in particular, have also been shown to be altered in schizophrenia, potentially in conjunction with Reelin." (PMID 26839720, 2016). "Their initial studies revealed a downregulation of about 50% of brain reelin expression levels in both schizophrenia and bipolar disorder." (PMID 26941609, 2016). "In particular, increased semaphorin 3A and decreased Reelin expression were detected in the cerebellum of subjects with schizophrenia, while altered expression of multiple members of the semaphorin family was observed in the prefrontal cortex." (PMID 26839720, 2016). "Following the initial observation that REELIN mRNA levels are reduced in patients with schizophrenia, several investigators reported a deficiency in Reelin expression in different groups of psychiatric subjects, including those with bipolar disorder." (PMID 27303268, 2016). "The mechanisms controlling Reelin expression are poorly understood and have been mostly gathered from tumours and from post-mortem schizophrenia brains." (PMID 27071537, 2016). "Overexpression of reelin also prevents the development of behavioral alterations related to schizophrenia and bipolar disorder, and delays amyloid-beta fibril formation and rescues cognitive deficits in an animal model of Alzheimer’s disease." (PMID 26941609, 2016). "The potential contribution of decreased Reelin expression to dendritic spine decreases in schizophrenia has long been postulated." (PMID 26839720, 2016). "Reelin expression is reduced in various regions in the post-mortem brain of schizophrenia patients but the exact role of reelin function in the neurobiology of schizophrenia remains elusive." (PMID 27602387, 2016). "Perhaps one of the most well-replicated findings in the pathophysiology of schizophrenia and, incidentally, autism is a disruption of Reelin expression." (PMID 26839720, 2016). "Among the several molecular candidates for the physiopathology of schizophrenia, clinical and preclinical evidence indicates reelin is a relevant component." (PMID 26968981, 2016). "The glycoprotein Reelin is arguably one of the ECM molecules most extensively investigated in schizophrenia and other psychiatric disorders." (PMID 26839720, 2016). "Among molecular candidates involved in the development of schizophrenia, reelin seems to be an important link between prenatal stress and cellular and physiological alterations observed in schizophrenia." (PMID 26968981, 2016). "Together, this evidence suggests a critical role for reelin in the deficits observed in schizophrenia." (PMID 26968981, 2016). "Rather, what they found was that the shorter isoform of RELN was significantly reduced in bipolar samples and an allelic imbalance of RELN expression in schizophrenia samples." (PMID 26696825, 2015).
schizophrenia (continued). "Reelin signalling contributes to multiple processes relevant to the pathogenesis of schizophrenia and BD: in development, it is involved in regulating neuronal migration and brain lamination and in the adult brain it modulates synaptic plasticity." (PMID 25708817, 2015). "Further work is needed to understand the specific contributions of these different pathways in mediating the effects of reelin on behavior, as well as their relationship to specific neuropsychiatric disorders such as schizophrenia and depression." (PMID 25762938, 2015). "RELN expression is downregulated in schizophrenia, bipolar disorders, autism, and Alzheimer’s disease." (PMID 26696825, 2015). "In order to study possible alterations in reelin blood levels in schizophrenia, we analyzed this signal in schizophrenic patients with a first episode hallucinatory and paranoid syndrome and control subjects in a pilot study design." (PMID 26305216, 2015). "The susceptibility genes (such as DISC1, RELN, GABA, SHANK3, NRXN1, NTNG1, etc.), which were associated with schizophrenia, also confer risk to ASD." (PMID 26204268, 2015). "Reelin levels were also shown to be decreased in schizophrenia and bipolar disorder, and altered with antipsychotic, antidepressant, and mood stabilizing medications." (PMID 25762938, 2015). "Along this line, Reelin signaling was found altered in several neurological disorders including depression, bipolar disorder, schizophrenia and autism." (PMID 25760459, 2015). "Several studies have suggested the possible role of reelin in the pathogenesis of human mental disorders such as schizophrenia, autism, bipolar disorder, and Alzheimer's disease." (PMID 25405877, 2014). "Several studies showed that abnormal reelin expression in the brain is involved in a number of neuropsychiatric disorders including lissencephaly, schizophrenia, and autism." (PMID 25237666, 2014). "Genetic and molecular evidences showed that reelin messenger-RNA and its protein are downregulated in cortical, hippocampal, and cerebellar neurons of patients suffering of schizophrenia and autism." (PMID 25237666, 2014). "A number of studies implicate the glycoprotein reelin in the etiology of several neurodevelopmental disorders such as schizophrenia, lissencephaly and autism." (PMID 23700474, 2013). "In conclusion, our data confirm that reelin mutant mice represent an interesting animal model for behavioral abnormalities seen in neurodevelopmental disorders like autism and schizophrenia and highlight the importance of reelin during development." (PMID 23700474, 2013). "The mRNA and protein expression of Reelin are decreased in patients with schizophrenia and bipolar disorder." (PMID 24409129, 2013). "Reelin is down-regulated in post-mortem brains from people with schizophrenia, with significant (approximately 50%) reelin reductions in hippocampus, caudate nuclei, and cerebellum." (PMID 23720610, 2013). "Additional examples include schizophrenia for RELN, GluR6, GRIN2A, GRIN2B, and CNTNAP2, childhood absence epilepsy for GABRB3, ADHD and depression for 5-HTT, and major depression for TPH2." (PMID 23935565, 2013). "Post-mortem studies have reported decreased levels of reelin and its message in patients with autism, schizophrenia, and bipolar disorder, with less consistent findings for depression." (PMID 23110844, 2012). "Several reports implicate reelin signaling in the etiology of neurodevelopmental and psychiatric disorders, including autism, schizophrenia, bipolar disorder, and depression." (PMID 23110844, 2012). "Thisreduction of RELN expression in schizophrenia and bipolarpost-mortem brain tissues was considered among the most consistent molecularfindings in these diseases." (PMID 21603580, 2011). "Nonetheless, we had two observationsthat suggest dysfunction of reelin in schizophrenia and bipolar disorder." (PMID 21603580, 2011).
schizophrenia (continued). "To further clarify the connection between RELN and psychiatricdisorders such as schizophrenia and bipolar disorder we studied the factors thatinfluence the expression of RELN and its different isoforms." (PMID 21603580, 2011). "We examined the total expression of RELN,allelic expression, and two alternative RELN isoforms inpostmortem brain samples from patients with schizophrenia and bipolar disorder,as well as unaffected controls." (PMID 21603580, 2011). "Studies of postmortem brain tissues from schizophrenia patients showed a clearreduction of RELN mRNA and protein levels, of up to 50%." (PMID 21603580, 2011). "Putative candidate schizophrenia genes like neuregulin/ErbB4 and reelin have important roles in migration of new neurons, and some studies have implied a reduction in neurogenesis in the schizophrenic brain." (PMID 21966452, 2011). "Reelin is down-regulated in the brain of schizophrenia, autism, and mood disorders, and is also expressed in blood plasma." (PMID 20414372, 2010). "Our results indicate that E17-MAM exposure reproduces findings from the hippocampal formation and the mediodorsal thalamus of patients with schizophrenia while providing little support for reelin's involvement." (PMID 20421980, 2010). "This is consistent with results that hyper-methylation of the RELN promoter and subsequent low expression of the reelin gene in the frontal lobes is correlated with schizophrenia." (PMID 21358990, 2010). "Reelin levels and its processing are also altered in blood plasma of schizophrenia, autism, and mood disorders." (PMID 20414372, 2010). "For example, examination of postmortem tissue from patients with schizophrenia revealed a 50% decrease in reelin levels, a decrease dendritic spine density, and a decrease in the number of NADPHd- or NOS-positive neurons." (PMID 21331324, 2010). "Particularly those associated with deregulation of NMDARs homeostasis and lower expression levels of reelin, such as schizophrenia." (PMID 19430527, 2009). "Reelin is a large secreted protein of the extracellular matrix that has been proposed to participate to the etiology of schizophrenia." (PMID 19430527, 2009). "Analyses of postmortem brains of patients with schizophrenia have shown consistent reduction of reelin, PV, and GAD67, the 67-kilodalton isoform of glutamic acid decarboxylase." (PMID 18439259, 2008). "The expression of reelin mRNA was decreased in GABAergic interneurons in layers I, II and IV of schizophrenia patients." (PMID 18439259, 2008). "Following a diet with L-methionine, a precursor in the biosynthesis of SAM, the reeler mouse (a model for schizophrenia) showed increased promoter methylation of the reelin gene, reduced reelin expression and a declined prepulse inhibition of startle." (PMID 19412416, 2007). "Hence, it is necessary to screen Indian patients with psychotic disorders to get a true picture of the contribution of Reelin (RELN) mRNA expression in schizophrenia." (PMID 39897195, 2025). "Studies in schizophrenia show that RELN hypermethylation reduces reelin expression and disrupts synaptic plasticity and neuronal migration; COMT methylation alters dopamine metabolism; and BDNF methylation is associated with cognitive impairment and negative symptoms." (PMID 41234420, 2025). "Specifically, it has been found that individuals with schizophrenia may have lower levels of RELN in some areas of the brain, such as the prefrontal cortex and hippocampus." (PMID 39897195, 2025). "Our study also showed that dysregulation of RELN expression may contribute to the pathophysiology of schizophrenia." (PMID 39897195, 2025). "The levels of RELN mRNA expression were decreased in schizophrenia." (PMID 39897195, 2025). "Amplified ADAMTS2 activity may potentially lead to Reelin inactivation, which has also been suggested to play a role in schizophrenia." (PMID 40837410, 2025).
schizophrenia (continued). "Interestingly, reduced expression of parvalbumin, GAD67, and reelin are highly replicated findings in the brains of schizophrenia patients." (PMID 40257019, 2025). "The RELN gene analysis should have been done at the onset of schizophrenia and after treatment." (PMID 39897195, 2025). "Reelin activity in the brain in patients diagnosed with schizophrenia, bipolar disorder and depression may be reduced by 30–50%." (PMID 39064075, 2024). "Interestingly, mice exhibiting reelin overexpression outperformed their counterparts in tasks, highlighting the significance of the reelin signaling pathway as a promising target for schizophrenia treatment." (PMID 38137152, 2023). "A two-fold reduction in both GAD-67 and reelin mRNA in GABAergic interneurons isolated from layer I of the cerebral cortex of patients with schizophrenia could be the result of a three-fold increase in DNMT1 activity." (PMID 38137152, 2023). "Altered reelin expression may result in the impairment of neuronal connectivity and synaptic plasticity, leading to the cognitive deficits observed in schizophrenia." (PMID 36980961, 2023). "A decrease in reelin expression might be a crucial trigger or vulnerability factor in developing schizophrenia." (PMID 38137152, 2023). "Similarly, engaging several research centers and laboratories, a significant decrease in the expression of reelin mRNA was once again confirmed in the prefrontal cortex of post-mortem patients with schizophrenia." (PMID 38137152, 2023). "Some evidence indicates that DNMT inhibitors might regulate the expression of some genes related to schizophrenia (Reelin (RELN), GAD1)." (PMID 36979236, 2023). "Indeed, in addition to RELN DNA hypermethylation, up to 50% downregulation of Reelin expression has been frequently identified in the cortex and hippocampus of schizophrenia patients." (PMID 36979424, 2023). "Neuronal migration and glial abnormalities due to dysfunctional reelin and chondroitin-sulfate proteoglycans may be additional contributors to the pathology of schizophrenia." (PMID 37189830, 2023). "Examination of peripheral blood lymphocytes in patients with schizophrenia expressed low activity of very low-density lipoprotein receptor (VLDLR) for reelin in drug-naive, unmedicated patients, and unchanged activity of apolipoprotein E receptor type 2 (ApoER2)." (PMID 38137152, 2023). "Despite the involvement of the striatum (including the nucleus accumbens) and its circuitry in psychiatric disorders such as major depression, schizophrenia, and obsessive-compulsive disorder, few studies addressing how Reelin influences striatal structure and circuits are available." (PMID 37153634, 2023). "There are diverse rodent models of schizophrenia that mimic patient symptoms based on various causal theories; however, likely shared reelin alterations have not yet been systematically assessed in those models." (PMID 35401125, 2022). "Genetic changes in RELN gene can result in abnormal reelin signalling leading to different pathological conditions such as bipolar disease, schizophrenia and autism.The physiological significance of the reelin in bone metabolism is generally not well understood." (PMID 35658052, 2022). "Furthermore, the expression levels of RELN mRNA in the whole blood of untreated schizophrenia patients were significantly lower than those in healthy controls." (PMID 35163751, 2022). "However, studies focused on the RELN gene differed from our findings, as they showed significant hypermethylation amongst patients with Schizophrenia." (PMID 36216926, 2022). "We conclude that reelin is an altered preclinical biomarker common to all models included, mainly prenatal or genetic models, and a key protein in schizophrenia disease, making the reelin signaling pathway in prenatal stages a target of special interest for future preclinical and clinical studies." (PMID 35401125, 2022).